HIF1A (hypoxia inducible factor 1 subunit alpha)
Diseases named in the same sentence as HIF1A in open-access papers (continued):
Sharing a sentence is not in itself a finding about the gene and the disease.
tumor (continued). "This study explores the mechanism by which NNT-AS1 influences the interaction of CAFs on glycolytic remodeling, proliferation, and metastasis of tumor cells through regulating miR-889-3p/HIF-1α, which also helps discover new clinical treatment targets for PDAC." (PMID 38521881, 2024). "In addition, the expression of VEGF is also observed in the tumor spheroids regulated by HIF-1α, contributing to drug resistance." (PMID 38751938, 2024). "HIF-1α is mainly overexpressed in solid tumor types, where it, therefore, has a dual role in promoting angiogenesis, metastasis, and resistance to treatment, which are all critical in tumor progression." (PMID 39099978, 2024). "In clear cell renal cell carcinoma, glutamine consumption by tumor cells results in local glutamine deprivation in the extracellular space, which activates HIF-1α to trigger TAM secretion of immunosuppressive IL-23, promoting Treg proliferation and the expression of IL-10 and TGF-β." (PMID 38185636, 2024). "Furthermore, HIF‐1α knockdown significantly decreased tumor‐initiating capacity in vivo, as measured by tumorigenicity assay, which was rescued by overexpression of ODC1 and SRM." (PMID 39058337, 2024). "In addition, there existed a strong positive correlation (r = 0.778, P < 0.001) between the R2* value and the positivity staining rate of HIF-1α, indicating that the R2* value effectively evaluates the hypoxia situation within the tumor." (PMID 38395884, 2024). "SOD1, CAT, GPX1, and HIF-1α were significantly increased in the lungs of tumour-bearing mice." (PMID 39506978, 2024). "In addition, the activation of HIF-1α can also promote the tumor angiogenesis and metastasis by up regulating the expression of VEGF and MMP." (PMID 38650627, 2024). "SMURF2’s regulation of protein stability could impact HIF1α activity and, consequently, its role in promoting tumor progression and metastasis." (PMID 39697237, 2024). "Thus 2-methoxyestradiol is designed to disrupt the binding and stability of HIF-1α and in this way disrupt tumor growth." (PMID 39493156, 2024). "Notably, HIF-1α also participates in cancer tissue growth, invasion, and metastasis, further emphasizing the importance of blocking the HIF-1α/VEGF pathway to effectively inhibit tumor angiogenesis." (PMID 38611849, 2024). "Further studies show HIF-1α stabilization in hypoxic conditions may concurrently activate MIF and upregulate PD-L1 expression, conferring tumor survival in oxygen-deficient intratumoral environments." (PMID 38732068, 2024). "In addition to promoting tumor cell proliferation, leptin signaling activation upregulates cancer cell production and secretion of soluble VEGFA via NFκB, Sp1, and HIF-1α signaling to induce angiogenic sprouting into the growing tumor mass." (PMID 39439572, 2024). "In addition, HIF1α is also involved in the regulation of lipid metabolism and amino acid metabolism in tumor cells." (PMID 38195606, 2024). "Our results indicated predominant TGFBI expression in tumor cells positive for HIF1α and CA9." (PMID 39346536, 2024). "More importantly, it has been reported that hypoxia-activated HIF-1α participates in tumor metabolism and angiogenesis, and boosts the proliferation, invasion, and metastasis of tumors by activating the Notch pathway, a key regulatory signaling mechanism that governs the fate of tumor cells and EMT." (PMID 37588219, 2024). "Importantly, acetate supplementation restores IFN-γ production in hypoxic HIF1α-/- T cells and re-sensitizes HIF1α-/- tumor-bearing mice to ICBs, providing an effective strategy to overcome ICB resistance." (PMID 38260594, 2024). "Interrupting the HIF-1α/C/EBPδ axis might yet present a clinically interesting route to exploit the tumor-suppressive effects of C/EBPδ in hypoxic PDAC tumors." (PMID 39273396, 2024). "Lack of stabilisation of HIF-1α has been linked to reduced adaptation of tumour cells to hypoxic conditions." (PMID 38341408, 2024).
tumor (continued). "Based on our data, HIF-1α or VEGF immunophenotypes may be a useful tool to clarify MRI-PET imaging data distinguishing between GBM tumor progression and pseudoprogression." (PMID 39055895, 2024). "Furthermore, it has been shown that hypoxia-inducible factor 1 alpha (HIF1α) plays a role in elevating GLUT5 expression under the hypoxic conditions prevalent within tumor microenvironments." (PMID 39107723, 2024). "Therefore, the inhibition of the transcription factor-co-activator HIF-1α-p300/CBP interaction represents an attractive strategy to inhibit tumor growth under hypoxic conditions." (PMID 39407454, 2024). "Upregulation of HIF-1α activates many crucial cancer hallmarks such as angiogenesis, glucose metabolism, cell proliferation/viability, invasion and metastasis and has a crucial role in tumor survival and progression." (PMID 38576624, 2024). "In the tumors from the untreated control mice, exemplarily shown with the SK-N-AS xenografts, HIF1A was uniformly expressed at the tumor borders, stroma-associated regions lacking blood vessels, and within central islands in the xenograft tumors." (PMID 39458030, 2024). "Additionally, when a direct comparison of the RQ expression levels of both isoforms was performed, HIF-1α had unambiguously higher expression levels in comparison to its second isoform in 93.3% of all tumor samples." (PMID 38607072, 2024). "HIF1A overexpression, due to reduced glucose metabolism and increased lactate accumulation in hypoxic environments, creates a suitable condition around the tumor for both PD-1/PD-L1 interaction and immunosuppression of CD8+ T cells." (PMID 38462658, 2024). "Increased expression of PIM1 in vivo can trigger the expression of HIF-1α target genes (VEGF and HK2) by directly phosphorylating HIF-1α at threonine 455, thereby inducing angiogenesis; however, VEGF is notably deficient in HIF-1α-knockdown tumor tissues." (PMID 37588219, 2024). "At a molecular level, the intratumoral bacterial load in lung cancer tissues was positively correlated with the gene expression of HIF-1A and VEGF-A in cancer cells, whose encoded proteins promote tumor hypoxia and angiogenesis, respectively, thus leading to cancer progression." (PMID 39120310, 2024). "HIF‐1α inhibition in combination with anti‐angiogenic therapy is a promising anti‐tumor strategy." (PMID 38400671, 2024). "Moreover, the chronic inflammation and oxidative stress associated with these conditions activate pro-inflammatory pathways like NF-κB and transcription factors such as HIF-1α, enhancing tumor angiogenesis, metastasis, and overall progression." (PMID 39290325, 2024). "The HDAC1 may activate the HIF1α/vascular endothelial growth factor A signaling pathway by directly inhibiting the ubiquitination of HIF1α, which can promote tumor angiogenesis." (PMID 39876842, 2024). "The WB results demonstrated that the expression levels of HIF-1α and PD-L1 were significantly elevated in tumor tissues compared to adjacent normal tissues, and the high expression of HIF-1α was often accompanied by the high expression of PD-L1 in tumor tissues." (PMID 38612546, 2024). "Notably, in HK2-depleted glioblastoma cells, tumor cell proliferation and angiogenesis were significantly inhibited, but invasion was increased; nonetheless, HIF-1α and VEGF also exhibited reduced expression." (PMID 39227970, 2024). "Firstly, we identified that in contrast to the tumor tissue, where we found a moderate correlation between HIF-1α and HIF-2α, but such an association was not valid in the peritumoral tissue." (PMID 38607072, 2024). "Moreover, NPs relieved tumor hypoxia two times according to pimonidazole marker analysis and drastically decreased expression levels of HIF1α and VEGF." (PMID 38794298, 2024).
tumor (continued). "In the context of GBM, HIF-1a plays a role in regulating tumor metabolism and increases GBM aggressiveness by promoting angiogenesis via upregulation of vascular endothelial growth factor (VEGF), erythropoietin (EPO), and platelet-derived growth factor (PDGF) family proteins." (PMID 38727262, 2024). "However, co-exposure of GBM cells to TmHg and TMZ reduced tumor growth-related factors, HIF-1α and VEGF, and p-STAT3." (PMID 39055895, 2024). "Hypoxic conditions and HIF1α signaling have a pro-angiogenic effect and contribute to the formation of endothelial cells, which improves the delivery of oxygen and nutrients to the tumor." (PMID 38344066, 2024). "In the early stages of tumor growth, HIF-1α induces TGF-β via an autocrine loop, activating Gal-9." (PMID 38542288, 2024). "HIF-1α is like a common “estuary” for many rivers, and the study of drugs targeting this key site has a multiplier effect on controlling the metabolic reprogramming of tumor cells." (PMID 39496001, 2024). "Additionally, tricin inhibits the VEGF expression by preventing the accumulation of HIF-1α in tumor cells." (PMID 38611849, 2024). "Interestingly, therapeutic efforts targeting HIF-1α have demonstrated promising results in reducing VEGF-mediated tumor progression." (PMID 38542288, 2024). "Considering previous studies demonstrating HIF-1α can directly regulate expression of T cell activation-related genes such as CD69 in tumor-infiltrating lymphocytes, it would be informative to examine how PX-478 impacts levels of canonical activation markers on mesoCAR T cells." (PMID 38425341, 2024). "It is speculated that HIF-1α leads to tumor regression because HIF-1α is often lost or rearranged in RCC cell lines." (PMID 39748950, 2024). "To explore TAGLN and HDAC2 expression in GBM patient surgical specimens, we performed IHC staining and observed that HDAC2 (which is a hypoxia‐related gene), TAGLN, CA9 (a hypoxic marker), and HIF1α were all located in GBM tumor cell nuclei and highly expressed in pseudopalisades (upper)." (PMID 38087889, 2024). "In breast cancer, MSC-derived exosomes induce a significant and dose-dependent decrease in the expression and secretion of VEGF through the modulation of the mTOR/HIF-1α signaling axis, suggesting an important potential therapeutic target for this type of tumor." (PMID 38725568, 2024). "One could think of using pharmacological inhibitors of PHD2/3, but these would have the drawback of upregulating HIF-1α in all cells, including tumor cells, thereby promoting tumor growth." (PMID 39242595, 2024). "Reduced activity of succinate dehydrogenase and fumarate hydratase in HCC triggers the accumulation of succinate and fumaric acid, which in turn stabilizes HIF-1α, initiating glycolytic activation and angiogenesis while hindering the function of anti-tumor immunity." (PMID 39085965, 2024). "Hypoxia has been shown to be responsible for tumour recurrence, being also a promoter of angiogenesis and distant metastasis in solid tumours, as identified through the functions of hypoxia-inducible factor-1α (HIF-1α)." (PMID 38920676, 2024). "In most cases, HIF-1α is an RCC tumor suppressor and HIF-2α is a carcinogenic factor in RCC." (PMID 39748950, 2024). "Moreover, tumor cells can inhibit apoptosis in adverse oxygen conditions by interacting with HIF1-α and members of the Bcl-2 family." (PMID 38727322, 2024). "The HIF-1α pathway plays a major role in tumors and promotes tumor progression." (PMID 38560503, 2024). "The GBM TME is characterized by abnormal vasculature, with poor blood flow at the level of the tumoral core, causing a decrease in oxygenation, increasing the expression of hypoxia-inducible factor 1-α (HIF1-α) and promoting angiogenesis and tumor cell invasion." (PMID 39409094, 2024). "Glycolysis is the main energy supply mode of tumor cells, and it is regulated by HIF1a." (PMID 38622131, 2024).
tumor (continued). "However, our findings indicate an improvement in anti-tumor T-cell function observed when stabilizing HIF-1α through the knockout of PHD2/3 in T cells." (PMID 39242595, 2024). "TAMs, induced by tumor activated HIF1α, could secrete IL-23, thereby promoting the proliferation of Tregs and the expression of IL-10 and TGF-β." (PMID 38957393, 2024). "A recent study indicated that tumor-infiltrating neutrophils could upregulate glycolytic factors and HIF-1α expression which then promoted PC progression." (PMID 38581008, 2024). "In addition, miRNA sponge for miR-23b can reduce GBM tumor malignancy, through the downregulation of HIF-1α, VEGF, and other molecules, suggesting miR-23 as a promising anticancer therapy either alone or in combination with current targeted therapies." (PMID 39055895, 2024). "Cardenolides like uscharin, calotropin, calactin, 2′‐oxovoruscharin, 19‐dihydrocalactin, 19‐dihydrocalotoxin, 15‐β hydroxy uscharin, asclepin and calotropagenin have been known to inhibit Na+/K+ATPase and HIF‐1α activity, which are important for tumour metastasis." (PMID 38400579, 2024). "Targeting HIF-1α downstream pathways: The suppression of tumor growth and improvement in treatment outcomes can be achieved by inhibiting HIF-1α-regulated genes involved in angiogenesis (e.g., vascular endothelial growth factor (VEGF) inhibitors) or glycolysis (e.g., glycolytic enzyme inhibitors)." (PMID 39099978, 2024). "Application of miRNA sponge for miR-23b in GBM was found to reduce tumor malignancy, through the downregulation of HIF-1α, VEGF, and other molecules, suggesting miR-23 as a promising anticancer therapy either alone or in combination with current targeted therapies." (PMID 39055895, 2024). "In oxygen-deficient TME, the PI3K/Akt/HIF-1α signaling axis is activated and further regulates the process of glycolysis, and the alteration of HIF-1α and glycolysis promote the proliferation of tumor cells." (PMID 38575922, 2024). "Excess copper stabilized HIF-1α, the rate-limiting component of HIF-1, causing its accumulation in the cytoplasm, which activated HIF-75, regulated vascular endothelial growth factor(VEGF)expression, and promoted tumor angiogenesis." (PMID 39539553, 2024). "HIF‐1α is a well‐defined hypoxia‐responsive factor regulating various biological processes, including angiogenesis, cellular metabolism, drug resistance and proliferation in tumour cells." (PMID 38229475, 2024). "Notably, NSCLC patients with positive HIF-1α expression in their tumor tissues had lower overall survival rates compared with those with negative HIF-1α expression." (PMID 39858431, 2024). "Indeed, we noted a consistency between the heightened NIR-II fluorescence intensity emitted by BC@Z-M and the elevated hypoxia, as indicated by HIF-1α staining, in the tumor tissue." (PMID 39613774, 2024). "In mammary stromal cells, HIF-1α is a negative regulator of tumour development." (PMID 38352889, 2024). "SMURF2’s tumor suppressor properties extend beyond HIF1α regulation." (PMID 39697237, 2024). "In RCC, activation of the mTOR pathway, downstream of the PI3-K/AKT pathway, leads to carcinogenesis by directly promoting the growth of tumor cells or by increasing the expression of hypoxia-inducible factor (HIF)-1α and HIF-2α, which are also involved in renal tumorigenesis." (PMID 39100549, 2024). "Hypoxic environments may activate several signaling pathways, including hypoxia-inducible factor 1α (HIF-1α), which supports tumor proliferation." (PMID 39612383, 2024). "In the tumor microenvironment, however, HIF-1α is pivotal in reprogramming glucose metabolism." (PMID 39906672, 2024). "Immunohistochemical staining analysis of the expression of tumor-specific proteins such as HIF-1α, NF-κB, and Ki67 showed that Prop could significantly inhibit the expression of three proteins (P<0.05)." (PMID 39525113, 2024). "In hypoxic environments, HIF1A promotes the drug resistance and metastasis of tumor cells." (PMID 38462658, 2024).
tumor (continued). "In addition, patients with CRC had higher levels of HIF-1α in their peripheral blood, the tumor microenvironment, and tumor-draining lymph nodes." (PMID 39410090, 2024). "HIF-1α enhances the expression of MCT in the plasma membrane of tumor cells." (PMID 38542288, 2024). "In order to understand how the modulation of HIF-1α signaling in adoptively transferred CD8 T cells affects their function in vivo when facing an immunosuppressive tumor microenvironment, we modulated the HIF-1α signaling in CD8 T cells and assessed their in vivo anti-tumor function." (PMID 39242595, 2024). "For further therapy evaluation, tumour tissue was stained with HIF1α antibody." (PMID 39061796, 2024). "However, continuous anti-angiogenesis therapy increases tumor hypoxia and leads to increased performance of HIF-1α, which in turn promotes the production of pro-angiogenesis genes and causes tumor resistance to anti-angiogenesis therapy." (PMID 39439453, 2024). "DYB‐03 showed promising antitumor activity in a xenograft tumor model by promoting apoptosis and inhibiting angiogenesis, which could be almost abolished by the deletion of HIF‐1α and EZH2." (PMID 38072662, 2024). "Moreover, the clinical significance of HIF-1α in NSCLC varied depending on tumor stage and lymph node involvement." (PMID 38609977, 2024). "Under hypoxic conditions, HIF1α stabilizes and translocate to the nucleus, where it activates transcription of genes involved in glycolysis, angiogenesis, and survival pathways that support tumor growth and resilience." (PMID 39697237, 2024). "In addition, the HIF-1α/vascular endothelial growth factor (VEGF) signaling cascade plays a pivotal role in coordinating tumor angiogenesis, cellular proliferation, and metastasis." (PMID 39339168, 2024). "This interaction suggests that SMURF2 could play a role in destabilizing HIF1α-related signaling, thereby indirectly affecting the tumor’s adaptation to hypoxic conditions." (PMID 39697237, 2024). "Moreover, CAF-derived exosomes can also deliver non-coding RNAs to target HIF-1α to regulate stem cell properties and glycolysis, thereby regulating tumor progression." (PMID 39578849, 2024). "Consequently, acetate supplementation, by restoring [acetyl-CoA] and AICD in Hif1α–/– T cells, resensitizes Hif1α–/– tumor-bearing mice to ICB therapy." (PMID 39477954, 2024). "However, to the extent that tumor tissue can continue to grow in this hypoxic environment, HIF-1α performs an essential role in the process." (PMID 37588219, 2024). "However, hypoxia is characteristic of the tumor microenvironment, where hypoxia-inducible factor 1 alpha (HIF-1α) is required to control metabolic reprogramming via close crosstalk between the mitochondria and HIF-1α." (PMID 39273044, 2024). "However, it is unlikely that LW6 promotes glucose uptake via HIF-1α inhibition, because HIF-1α promotes glucose uptake in many tumor cells by increasing GLUT1 expression." (PMID 38339168, 2024). "CAR also curbed HIF-1α and β-catenin tumor levels subsequently suppressing ALDH-1 and SOX2." (PMID 38962320, 2024). "This link between the tumor cell hypoxic response and immune-suppression is corroborated by evidence that HIF1a activation in tumor cells results in a mesenchymal shift and expression of immunosuppressive genes and is linked with poor patient survival and tumor recurrence." (PMID 38774283, 2024). "It would also stabilize HIF-1α in other immune cells, potentially impairing anti-tumor immunity." (PMID 39242595, 2024). "In this study, propofol downregulated HIF-1α in tumor tissue." (PMID 39525113, 2024). "In addition, downregulation of HIF-1α in RCC cells promotes tumor growth, and supplementing HIF-1α deficient cell lines with HIF-1α leads to tumor regression." (PMID 39748950, 2024).